ACOX3 (acyl-CoA oxidase 3, pristanoyl)
Description:
Involved in peroxisomal beta-oxidation of branched-chain fatty acids (BCFAs). Catalyzes the initial and rate-limiting dehydrogenation step that removes two hydrogen molecules and introduces a trans double bond between the alpha and beta carbons of the acyl CoA molecules while generating hydrogen peroxide as a by-product. Metabolizes multi-methyl-branched fatty acyl-CoA esters such as (2S)-pristanoyl-CoA, displaying redundancy with ACOX3. Can oxidize straight-chain mono- and dicarboxylyl fatty acyl-CoAs with lower efficiency (By similarity). Oxidizes the CoA-esters of 2-methyl-branched fatty acids.
Tractability: PROTAC: ubiquitination databases record sites on it; its protein half-life has been measured; a small molecule that binds it is known.
Target class: Enzyme; Oxidoreductase
Gene: Protein-coding gene on chromosome 4 (8,365,885 to 8,440,750, reverse strand). Ensembl gene ENSG00000087008.
Subcellular location: Peroxisome
Subcellular location (Human Protein Atlas): Peroxisomes
Pathways (Reactome):
Metabolism: Beta-oxidation of pristanoyl-CoA
Protein localization: Peroxisomal protein import
Gene Ontology:
Molecular function: acyl-CoA oxidase activity; fatty acid binding; flavin adenine dinucleotide binding; pristanoyl-CoA oxidase activity; FAD binding; long-chain fatty acyl-CoA oxidase activity; medium-chain fatty acyl-CoA oxidase activity; oxidoreductase activity, acting on the CH-CH group of donors; very-long-chain fatty acyl-CoA oxidase activity
Biological process: fatty acid beta-oxidation using acyl-CoA oxidase; fatty acid beta-oxidation; fatty acid metabolic process
Cellular component: membrane; peroxisome; cytosol; peroxisomal matrix
Genetic constraint (gnomAD): Loss-of-function variants: 72 observed, 78.65 expected, observed/expected ratio (o/e) 0.92, 90% interval 0.76 to 1.11. The upper end of that interval is the gene's LOEUF score, 1.11, which puts it in group 4 of 6, group 1 being the genes least tolerant of losing a copy. Missense variants: 944 observed, 936.75 expected, observed/expected ratio (o/e) 1.01, 90% interval 0.95 to 1.06. Synonymous variants: 385 observed, 378.64 expected, observed/expected ratio (o/e) 1.02, 90% interval 0.94 to 1.11.
Homologues: Orthologues: chimpanzee ACOX3 (94% identical), macaque ACOX3 (85% identical), dog ACOX3 (76% identical), guinea pig ACOX3 (76% identical), rat Acox3 (76% identical), pig ACOX3 (74% identical), mouse Acox3 (73% identical), tropical clawed frog acox3 (67% identical), zebrafish acox3 (64% identical), Drosophila melanogaster Acox3 (42% identical), Caenorhabditis elegans acox-3 (37% identical). Paralogues in human: ACOX2 (24% identical), ACOX1 (23% identical), ACOXL (18% identical), ACAD9 (16% identical), ACADVL (16% identical), ACADS (15% identical), ACADSB (14% identical), ACAD8 (14% identical), GCDH (13% identical), ACADM (13% identical), IVD (12% identical), ACADL (12% identical), and 2 more.
Diseases named in the same sentence as ACOX3 in open-access papers:
ACOX3 is named in the same sentence as 15 diseases in open-access papers, as found by Europe PMC text mining. Sharing a sentence is not in itself a finding about the gene and the disease. The quoted sentences say what the papers report.
breast carcinoma (2 papers, 2022 to 2026). "Considering our results and previous studies, PLXNB2 and ACOX3 are proposed as universal prognostic markers of breast cancer associated with chemotherapy resistance." (PMID 35335125, 2022). "Results showed that four acyl-CoA synthetases—GCDH, ACSS2, ACOX1, and ACOX3—were significantly down-regulated in breast cancer cells, with ACSS2 showing the most pronounced reduction." (PMID 41544165, 2026). "This suggests that ACOX3 can be a potential prognostic marker in breast cancer and drug resistance, although prognostic performance of ACOX3 should be confirmed in future experiments." (PMID 35335125, 2022). "On the other hand, ACOX2, known to be related to ACOX3, is proposed as a promising prognostic marker in hepatocellular carcinoma and breast carcinomas." (PMID 35335125, 2022). "Interestingly, the prognostic role of ACOX3 in breast cancer as well as other cancers is unclear." (PMID 35335125, 2022).
prostate carcinoma (2 papers, 2014 to 2022). A carcinoma that arises from epithelial cells of the prostate gland. "Although ACOX3 is highly expressed in human prostate cancer tissue compared with paired normal tissues, very low levels of expression are shown in other organs." (PMID 35335125, 2022). "Alpha-methylacyl-CoA racemase (AMACR), pristanoyl-CoA oxidase (ACOX-3) and D-bifunctional protein (DBP), are also important fatty acid oxidation-related proteins in prostate cancer, and we also included them in our analysis." (PMID 24886074, 2014). "We also observed that proteins involved in fatty acid oxidation, such as AMACR, ACOX-3 and DBP, were restricted to the tumour cells, which is consistent with the presence of a metabolic pathway different from glycolysis, and compatible with oxidative phosphorylation in prostate cancer cells." (PMID 24886074, 2014).
colitis (1 paper, 2019). Inflammation of the colon. "RT‐PCR and IHC analysis validated that TOE up‐regulated the expression of Adh5, Aldh3a2 and Acox3, but down‐regulated the expression of CCL20, CXCL5, CCR6 and CXCL1 in DSS‐induced colitis." (PMID 31565850, 2019).
hypothyroidism (1 paper, 2023). Abnormally low levels of thyroid hormone. "In cytoplasm, single ACOX3-positive peroxisomes increase was apparent only on day 7 of hypothyroidism." (PMID 37153362, 2023). "ACOX3 protein expression decreased after 7 days but returned to the control level on day 21 of hypothyroidism." (PMID 37153362, 2023). "We further analysed ACOX1 and ACOX3 localization patterns and their colocalization within peroxisomes of single brown adipocytes over the course of hypothyroidism." (PMID 37153362, 2023). "Most of the ACOX1 positive peroxisomes were single ACOX1-positive, although the number of double ACOX1/ACOX3-positive peroxisomes was substantial, and also increased in hypothyroidism." (PMID 37153362, 2023). "Closely adjacent to the ER, ACOX3-positive peroxisomes showed exclusive pattern: absence on day 15, single ACOX3-positive peroxisomes presence on day 7, and double ACOX1/ACOX3-positive peroxisomes presence in euthyroid control and on days 7 and 21 of hypothyroidism." (PMID 37153362, 2023). "The number of single ACOX1-positive peroxisomes closely adjacent to MTH/LB was expectedly lower, and increase in number of ACOX1-positive peroxisomes (both single ACOX1 and double ACOX1/ACOX3-positive peroxisomes) was noticeable only on day 7 of hypothyroidism (figures 3b1, b2 and 4a)." (PMID 37153362, 2023). "A plausible explanation for the reduced ACOX3 expression in the early days of hypothyroidism may lay in the fact that hypothyroidism affects systemic lipid metabolism, which is reflected in the change of ACOX substrates for oxidation in BAT in favour of ACOX1." (PMID 37153362, 2023). "Like ACOX1, ACOX3-positive peroxisomes were predominantly adjacent to the LB and MTH and showed increase in number over the course of hypothyroidism, and this increase was biphasic with an exception of single ACOX3-positive peroxisomes closely adjacent to LB where increase was linear." (PMID 37153362, 2023). "On day 15 of hypothyroidism only single ACOX1-positive peroxisomes localized closely adjacent to the ER were present, while on other points of hypothyroidism, on days 7 and 21, we found both single ACOX1- and double ACOX1/ACOX3-positive peroxisomes." (PMID 37153362, 2023). "Herein, we demonstrated that hypothyroidism affects both ACOX1 and ACOX3 protein expression and induces their distinct tissue and cell heterogeneous localization/colocalization in BAT." (PMID 37153362, 2023). "We demonstrated ACOX3 presence in euthyroid rat BAT and its temporarily decreased levels in the early days of hypothyroidism." (PMID 37153362, 2023). "Therefore, we used methimazole-induced hypothyroidism to study ACOX1 and ACOX3 protein expression and their tissue immunolocalization." (PMID 37153362, 2023).
lung carcinoma (1 paper, 2021). "The advanced age, high expression of GAPDHS, low expressions of ACSBG1 and CYP4A11, and ACOX3 mutation were biomarkers of poor prognosis in lung cancers." (PMID 34970420, 2021). "The survival analysis was significant between mutation and wild-type groups of ACOX3 in lung cancers, which was associated with a worse prognosis of lung cancer (p < 0.05)." (PMID 34970420, 2021). "High expression of GAPDHS, low expression of ACSBG1, low expression of CYP4A11, mutated ACOX3, and old age predict a poor prognosis of lung cancer." (PMID 34970420, 2021). "In lung cancer tissue, high expression of GAPDHS, low expressions of ACSBG1, CYP4A11, mutated ACOX3, and old age predict a poor prognosis." (PMID 34970420, 2021).
psychosis (1 paper, 2020). "Peroxisomal dysregulation has been described in relation with psychotic symptoms, in the context of inborn errors of metabolism, so a possible direct effect of ACOX3 gene on conversion to psychosis could not be ruled out." (PMID 32754072, 2020).
cancer (6 papers, 2016 to 2025). A tumor composed of atypical neoplastic, often pleomorphic cells that invade other tissues. "One key family of enzymes in this process are the peroxisomal acyl-CoA oxidases (ACOX1, ACOX2 and ACOX3), the expression of which has been shown to be dysregulated in some cancers." (PMID 35999530, 2022). "The authors confirmed the downregulation of several genes in at least 7 cancer types, including ACOX3, PKC2, SLC27A4, and SLC27A2." (PMID 33562532, 2021). "Additionally, ACOX3, ACAD9, ACAD10, ACOT1, ACOT8, and DECR2 displayed positive associations with PEBP1/STK11 co-expression across various cancer types, highlighting a potential involvement in enhancing fatty acid metabolism in the context of PEBP1/STK11 expression." (PMID 40806276, 2025). "These include proteins that were previously associated with different types of cancer, of which mutation in one of them (ACOX3) was highly associated with a prediction of CLL outcome, while five proteins had no report connecting them to cancer." (PMID 27078856, 2016).
tumor (5 papers, 2014 to 2025). "Results showed that KPC tumor-induced increase in the mRNA levels of Fbxo32, Trim63, Map1lc3b, Cd36, Acox3, and spliced-Xbp1 (sXbp1) in skeletal muscle were significantly reduced by treatment of mice with 4μ8C." (PMID 40655023, 2025). "In parallel to a clear increase on MCT2 expression from non-tumour to localized tumour cells, we have also observed a rise in the expression of specific key proteins involved in peroxisomal β-oxidation: ACOX1 and ACOX3." (PMID 25639644, 2015).
ACOX3 also shares sentences with these, for which no sentence is quoted: Glucose intolerance (2 papers); Cirrhosis (1); Fanconi anemia (1); hepatocellular carcinoma (1); infection (1); steatosis (1); type 2 diabetes mellitus (1).